CDKN2A (cyclin dependent kinase inhibitor 2A)
Diseases named in the same sentence as CDKN2A in open-access papers (continued):
Sharing a sentence is not in itself a finding about the gene and the disease.
cancer (continued). "We also made similar observations for numerous other TSGs, particularly MLH1, TET2 and CDKN2A, with them often being hypermethylated much more frequently than mutated in numerous cancer types." (PMID 34871444, 2021). "In our cohort, we found a single ATC with a deleterious CDKN2A mutation as well as four additional tumors with gene deletions, and CDKN2A therefore constitutes the most aberrantly affected cancer-related gene in the entire cohort." (PMID 34944959, 2021). "It is plausible that the varying cancer types reported with CDKN2A genetic alterations can be distinguished by the different variant effects on p16INK4A and p14ARF, although evidence to date are limited and conflicting." (PMID 33766116, 2021). "The tumor suppressor p16 (INK4A/MTS-1/CDKN2A) has gained widespread importance in cancer research, because the loss of p16 is described as an early event in cancer progression; however, its induction is strongly associated with the induction of senescence." (PMID 34360651, 2021). "The inactivation of CDKN2A induced by homozygous deletion or promoter hyper-methylation and point mutation contributes to cancer progression in various cancers, like PDAC." (PMID 34205170, 2021). "Our findings underline the crucial role of the CDKN2A/B locus on chromosome 11 leading to strong cancer predisposition in dogs." (PMID 34946912, 2021). "The cancer genome spectrum showed sarcomatoid HCC group had significant higher mutation rates in CDKN2A, EPHA5, FANCM and MAP3K1." (PMID 34331411, 2021). "Our findings confirm a complex genetic basis of OSA, moderate heritability, and the crucial role of the CDKN2A/B locus leading to strong cancer predisposition in dogs." (PMID 34946912, 2021). "Dysregulation of the CDK4/6-Rb pathway, as with the activation of CCND1/CDK4 or CDKN2A loss, contributes to cancer development and confers resistance of cancer cells to treatment with the MAPK/ERK inhibitors." (PMID 33807122, 2021). "Compared to BRAF fusions, BRAFV600E tends to be more aggressive, more likely to be associated with CDKN2A/B deletions, and can transform cancers into higher-grade tumors." (PMID 33980169, 2021). "Overall, we identified a novel cancer-related gene CDKN2A, which encodes multiple tumor suppressor 1 (MTS1) and belongs to the INK4 family." (PMID 35004697, 2021). "This region contains 46 annotated genes and loci including the known cancer-associated cyclin-dependent kinase inhibitor encoding genes CDKN2A and CDKN2B." (PMID 34946912, 2021). "ERBB2, EGFR and KRAS have FDA-approved drugs for use in cancer therapy, whereas CDKN2A has biological evidence for targetability, but associated drugs are not yet standard-of-care." (PMID 34298611, 2021). "The inactivation of the p16/p14 locus (where genes associated with cancer control such as cyclin-dependent kinase inhibitor 2A (CDKN2A) and ARF are found) induces cell proliferation." (PMID 35052539, 2021). "CDKN2A-encoded proteins display essential roadblocks to cancer initiation, and CDKN2A ranks high within FPC susceptibility genes." (PMID 34680288, 2021). "The use of iPSCs from patients with a family history of cancer allowed us to mimic the potential risk associated with an inherited monoallelic variant of CDKN2A." (PMID 34680288, 2021). "Loss of heterozygosity has been reported in HPV-associated carcinomas, as have point mutations of CDKN2A or the silencing of the CDKN2A gene by promoter hypermethylation of the promoter." (PMID 33669021, 2021).
cancer (continued). "CDKN2A is frequently inactivated in cancers due to genetic alterations by point mutation, homozygous deletion, promoter hypermethylation, and loss of heterozygosity." (PMID 33322698, 2020). "Loss of either the CDKN2A locus or the entire CDKN2 cluster is frequently observed in human cancers." (PMID 32067956, 2020). "A prospective study examining cancer diagnoses in Swedish carriers of the Arg112dup alteration in CDKN2A concluded that mutation carriers had a significantly elevated risk of developing pancreatic, lung, head and neck, and gastro-oesophageal carcinomas." (PMID 33076392, 2020). "In some families, CDKN2A gene mutations facilitate the development of only one type of cancer, while in other families, they can lead to a cancer predisposition syndrome, increasing the risk of developing multiple types of cancer." (PMID 33167404, 2020). "CGH of 10 different cell lines revealed that the loss of the p16Ink4a/p19Arf-locus was the only common signature where the RT2.Cdkn2a−/−- or the RT2.CRISPR-Cdkn2a-cancer cells differed from the parental or the CRISPR-Cas9 control cell lines." (PMID 32165639, 2020). "Consistent with the mutual exclusive relationship between RB1 and CDKN2A gene alterations, the genes are inversely expressed in most cancers exhibiting frequent loss/mutation of RB1." (PMID 32242058, 2020). "Loss of the CDKN2a locus is the second most frequent copy number alteration that characterizes human tumors and cancer cell lines." (PMID 32698529, 2020). "To address this question, we generated Cdkn2a-deficient RT2-cancer cell lines through in vitro and in vivo selection." (PMID 32165639, 2020). "Loss of CDKN2A function by mutation or copy number loss is a major landmark in a variety of cancers." (PMID 32628820, 2020). "CDKN2A encodes for a cell-cycle regulator mutated in more common cancers like melanoma, and neurofibromatosis 2 (NF2) acts as tumor suppressor that is part of the NF2/Merlin complex that makes up the NF2/Hippo pathway." (PMID 32392897, 2020). "The CDKN2A/B locus that encodes p15INK4b, p16INK4a, and p14ARF is frequently methylated in human cancers (resulting in gene silencing)." (PMID 32183138, 2020). "Familial clustering of additional cancer types, such as CDKN2A-associated PC and p14arf-associated nervous system tumors, has long been described in CM families." (PMID 32325837, 2020). "CDKN2A is an important molecule in cells that regulates cells, and its loss has proved to be an important event in many types of cancer." (PMID 33174391, 2020). "Somatic mutations in CDKN2A or dysregulation of its functional activity are frequently detected in various types of human cancer." (PMID 32971832, 2020). "These highly methylated and lowly expressed genes, such as Ras association domain family member 1 (RASSF1A) and cyclin‐dependent kinase inhibitor 2A (CDKN2A), were predominantly enriched in multiple cancer‐associated signalling pathways." (PMID 31565863, 2019). "In human cancers with P16 loss (encoded by CDKN2A), cell cycle inhibitors are given (CDK4/6 inhibitors)." (PMID 31176307, 2019). "Loss of function of p16Ink4a (encoded by CDKN2A) or Rb (encoded by RB1) is generally mutually exclusive in cancer cells and each one promotes tumorigenesis." (PMID 30959874, 2019).
cancer (continued). "CDKN2A loss of function is seen in a number of different cancer types, with the majority of cases being inactivation by homozygous deletions, followed by less common inactivating mutations and promoter hypermethylation." (PMID 31528332, 2019). "Although elevated CIC formation was found in cancers with CDKN2A inactivation, a causal link between them remains to be established." (PMID 29904067, 2018). "Intact Rb is critical to the mechanism of CDK4/6 inhibition in cancer treatment, and CDKN2A loss with intact Rb mechanistically predicts sensitivity to CDK4/6 inhibitors." (PMID 30293995, 2018). "The CDKN2A/B locus is remarkable for the large number of associated diseases, ranging from aging and frailty to cancer to metabolic disease." (PMID 30087655, 2018). "Although there have been several reports that the frequency of CDKN2A promoter methylation is higher in EC samples than those from cancer-free controls, the association and the role of CDKN2A promoter methylation in EC remain controversial." (PMID 28637022, 2017). "Three genes were located between these two lncRNA genes: IFNE, MTAP, and CDKN2A, all of which are associated with cancer." (PMID 27903974, 2017). "Four carcinomas exhibited a missense mutation in the tumor suppressor CDKN2A, which was thus the second most frequently mutated gene." (PMID 27844328, 2017). "To date, the RB1 pathway in human cancers has been reported to be disrupted only by loss of expression of CDKN2A or RB1, as well as by CDK4/CCND1 over- expression, even though SWI/SNF is known to be an essential cofactor for RB1 function." (PMID 28105458, 2016). "From a literature search, we identified 17 publications that associate CDKN2A methylation with expression and/or cancer." (PMID 27170255, 2016). "p16 protein overexpression reportedly occurs in cancer owing to mutation of the CDKN2A gene or feedback control caused by loss of the Rb gene." (PMID 27410681, 2016). "One outstanding example was the prioritization of the previously studied SNP, rs11515, located in the 3’UTR of the tumor suppressor CDKN2A, which has clear associations with poor prognosis and risk in different cancers." (PMID 27029813, 2016). "In this series, there were a total of 29 cancers reported among the 14 patients from 12 unique families with germline CDKN2A mutations." (PMID 29263814, 2016). "Frequent CDKN2A deletions have been described in some human cancers while the overall frequency of mutations in CDKN2A in human cancer has been found to be only 3.8%." (PMID 27322425, 2016). "Somatic inactivation of the CDKN2A gene, a feature common to many cancer types involves point mutations, promoter methylation or deletions at the locus." (PMID 26909863, 2016). "For example, mutation to Cyclin-Dependent Kinase Inhibitor 2A (CDKN2A) facilitates herpes simplex virus (HSV) replication in cancer cells." (PMID 27533247, 2016). "The post-treatment cancer retained its pathogenic CDKN2A and SMARCA4 mutations and gained a low VAF, truncating ARID1A change." (PMID 27045317, 2016). "p16, encoded by the CDKN2A gene locus in chromosome 9p21, is frequently inactivated resulting in a complete block of gene transcription in cancer patients." (PMID 27528225, 2016). "The genetic or epigenetic inactivation of INK4A (CDKN2A) locus encoding the tumor suppressors p16INK4A and p14ARF has been frequently implicated in the pathogenesis of human cancer." (PMID 25784651, 2015).
cancer (continued). "Loss of copy number of p16/CDKN2A is a well recognised tumour suppressor gene involved in cancer oncogenic process, and has been reported to be associated with disease progression of cartilaginous tumours." (PMID 25432631, 2015). "Loss of the corresponding locus (CDKN2A) is among the most frequent cytogenetic alteration events in human cancer." (PMID 25986046, 2015). "CHD5 binds and regulates an extensive number of cancer-associated loci, including tumorigenic Cdkn2a, and other genes encoding proteins implicated in chromatin dynamics and cancer-associated pathways." (PMID 24454811, 2014). "The INK4A locus codes for two independent tumor suppressors, p14ARF and p16/CDKN2A, and is frequently mutated in many cancers." (PMID 24505435, 2014). "In the same percentage there is an intragenic mutation coupled with loss of the second allele, and in 15% of cases cancer occurs after a hypermethylation of the P16INK4A/CDKN2A gene promoter." (PMID 24084722, 2013). "The most frequent polymorphism in CDKN2A, a substitution in the 3′ UTR of a cytosine for a guanine base at cDNA nucleotide 500 (numbered from the p16INK4a initiation codon, rs11515), is associated with different cancer types." (PMID 22046342, 2011). "These have mostly involved cancer phenotypes because the cell-cycle regulators CDKN2A and CDKN2B are recognised to be involved in predisposition to certain cancers." (PMID 20386740, 2010). "By contrast, dosage events affecting genes that promote cancer in allele-independent manner, e.g. loss of CDKN2A or gain of MYC, were expected to display random somatic alterations of either allele." (PMID 20885788, 2010). "p19ARF is encoded by the cyclin-dependent kinase inhibitor 2a (Cdkn2a), and the human ortholog of Cdkn2a (CDKN2A) has been extensively examined in relation to cancer and aging." (PMID 19335888, 2009). "When considering all cancer types, pathogenic somatic variants in CDKN2A (identified in 12%.7 of CFTR PV carriers; Sidak‐corrected p = 0.0069) and CDKN2B (identified in 4.2% of CFTR PV carriers; Sidak p = 0.0428) were more common in our cohort of CFTR PV carriers than in the global COSMIC database." (PMID 41147257, 2025). "The gene’s role in immune regulation and its association with immune checkpoints like PD-1 suggest that CDKN2A could guide immunotherapy strategies, potentially improving responses in cancers where it is highly expressed." (PMID 39925808, 2025). "Finally, CDKN2A mutated families have shown also an increased risk to develop other type of cancers, like breast cancer." (PMID 40869905, 2025). "In some cancers, the high expression of CDKN2A is associated with poor prognosis." (PMID 40861807, 2025). "The negative β coefficient of CDKN2A in model 2 further confirmed that CDKN2A LoF may reduce risk of cancer progression." (PMID 39753721, 2025). "CDKN2A, as a cancer suppressor gene, was only mutated in 020G." (PMID 40244200, 2025). "This suggests that Cdkn2a knockout may allow damaged or mutated cells to survive, contributing to cancer progression, a mechanism that has been seen in colorectal cancer." (PMID 39605490, 2024).
cancer (continued). "This makes CDKN2A a good potential diagnostic biomarker in these 5 cancers primarily in COAD." (PMID 38894777, 2024). "p14, a splice variant of CDKN2A, is significantly associated with cancer poor prognosis." (PMID 38774759, 2024). "In this sense, CDKN2A can potentially be associated with a broad cancer predisposition phenotype." (PMID 38730621, 2024). "Interestingly, CDKN2A is also occasionally used preoperatively during diagnostic biopsy to predict cancer aggressiveness." (PMID 39590385, 2024). "However, CDKN2A gene upregulation has been associated with poor prognosis in COAD in terms of cancer location, which makes CDKN2A a potential prognostic biomarker." (PMID 38894777, 2024). "In this study, we aimed to investigate the gene expression and potential implications of CDKN2A across various types of cancer as it could be used as a diagnostic and prognostic biomarker." (PMID 38894777, 2024). "Multiple types of cancers have been linked to CDKN2A in scientific studies." (PMID 38206516, 2024). "As a main limitation of this pan-cancer analysis, further wet lab validation is needed to elucidate the precise mechanisms underlying the CDKN2A gene’s role in cancer pathogenesis and its therapeutic implications since this analysis was carried out based on public computational databases." (PMID 38894777, 2024). "Features ranked in the top five from each omic dataset also validated the capacity of our approach to recover well-established molecular processes associated with cancer, for example, CDKN2A copy number alterations, as well as sensitivity to the SRC family inhibitor, dasatinib." (PMID 39614072, 2024). "The frequency of CDKN2A loss-of-function has a wide range from 20% to 85% in various cancers." (PMID 36961395, 2023). "By shedding light on the particular mutations in CDKN2A that are associated with different types of cancer, researchers and clinicians can lay the groundwork for precision medicine approaches that tailor treatments to the unique genetic profiles of individual patients." (PMID 38137564, 2023). "CDKN2A alteration is a contributor of tumorigenesis, however, its overexpression was also reported in several types of cancers due to its association with aberrant apoptosis, senescence, angiogenesis and cancer migration." (PMID 37353799, 2023). "CDKN2A mutation was coupled with other genes mutation in different human cancers." (PMID 37626750, 2023). "For instance, genomic loss in the cancer cells of CDKN2A (encoding the cyclin-dependent kinase inhibitor p16INK4) and DPC4, encoding SMAD4, a central mediator of transforming growth factor (TGF)-β signaling, has been implicated in modifying the response to gemcitabine or 5-FU." (PMID 36831254, 2023). "CDKN2A is a highly prevalent gene mutation in human cancers, with three distinct mechanisms identified as potential contributors to its inactivation: genomic deletions, point mutations, and hypermethylation of the CDKN2A promoter region CpG island." (PMID 37950153, 2023). "Loss of CDKN2A could promote tumorigenesis and metastasis and indicate a poor prognosis in many cancers, including PCa." (PMID 36911392, 2023). "Recent studies have shown that CDKN2A is associated with poor prognoses in various cancers." (PMID 36902801, 2023). "We analyzed the associations between CDKN2A and 47 immune factors in pan-cancer." (PMID 36961395, 2023).